CTSG (cathepsin G)
Diseases named in the same sentence as CTSG in open-access papers (continued):
Sharing a sentence is not in itself a finding about the gene and the disease.
lung carcinoma (4 papers, 2017 to 2025). "Notably, CTSG has been associated with CD4 T cell activation in lung cancer." (PMID 39891665, 2025). "In this study, we are committed to excavating potent immune targets, and further explored the expression and clinical significance of CTSG in HIV-related lung cancer on the basis of a big data search for the expression and role of Cathepsin G in lung cancer." (PMID 39080685, 2024). "Meanwhile, the expression of CTSG protein in HIV-related lung cancer tissues was not only significantly lower than that in adjacent non-tumor tissues, but also lower than that in simple non-small cell lung cancer tissues." (PMID 39080685, 2024). "Future studies of CTSG-mediated novel HIV-related lung cancer treatment regimens may significantly improve the life span and quality of life of patients with HIV-related lung cancer." (PMID 39080685, 2024). "It is thus promising to see whether CTSG proteins, which are highly expressed in cancerous tissues, can inhibit lung cancer progression through the modification of tumor microvasculature and the regulation of tumor microenvironment (TME)." (PMID 39080685, 2024). "CTSG could potentially mitigate disease advancement in HIV-related lung cancer patients by inhibiting immune depletion, serving as a prospective immunotherapeutic target for both non-HIV and HIV-associated lung cancers." (PMID 39080685, 2024). "CTSG protein correlates with CD4 + T cell count, CD4 + T/CD8 + T cells, pathological type, distant metastasis and clinical stage in HIV-related lung cancer." (PMID 39080685, 2024). "An inhibitor of cathepsin G [Cathepsin G inhibitor I (Cat GI); CAS 429676-93-7] markedly induced TRAIL-mediated apoptosis in human renal carcinoma (Caki, ACHN, and A498), lung cancer (A549) and cervical cancer (Hela) cells." (PMID 29290980, 2017). "At present, the expression, function and regulatory role of CTSG in HIV-related lung cancer tissues have not been reported." (PMID 39080685, 2024). "CTSG expression in HIV-related lung cancer tissues was lower than in the adjacent non-tumor tissues and lower than in simple lung cancer." (PMID 39080685, 2024). "Through preliminary big data information retrieval, we found that the expression of Cathepsin G in lung cancer tissues was lower than that in non-tumor tissues, and the expression was different in different clinical stages and pathological types of lung cancer." (PMID 39080685, 2024). "CTSG protein expression in HIV-related lung cancer tissues was lower than in adjacent tissues and lower than in lung cancer tissues without HIV infection, with a statistically significant difference (P < 0.05)." (PMID 39080685, 2024). "This study aimed to examine the expression and clinical significance of Cathepsin G (CTSG) protein in both non-HIV and HIV-related lung cancers." (PMID 39080685, 2024). "Hematoxylin eosin (HE) staining and immunohistochemistry were used to detect the expression of CTSG protein in 45 cases of HIV-related lung cancer tissues, 52 cases of simple lung cancer tissues and their corresponding adjacent non-tumor tissues." (PMID 39080685, 2024). "Immunohistochemistry (IHC) was used to detect the expression of CTSG proteins in the pathological tissues of patients with HIV-related lung cancer and patients with lung cancer without co-infection, the Kaplan-Meier method was used for survival analysis." (PMID 39080685, 2024).
osteomyelitis (4 papers, 2019 to 2024). An acute or chronic inflammation of the bone and its structures due to infection with pyogenic bacteria. "The CTSG N125S polymorphism was in Hardy–Weinberg equilibrium among patients with osteomyelitis and controls." (PMID 31647805, 2019). "The CTSG N125S variant G allele was also more frequent among osteomyelitis patients (8.1% vs 4.7%, χ2 = 7.12, OR = 1.78, 95% CI = 1.14–2.78, p = 0.0076 by the Mantel-Haenszel test, χ2 = 6.56, P = 0.01 by the Yates correction)." (PMID 31647805, 2019). "Frequency of CTSG N125S (rs 45567233) alleles in osteomyelitis (OM) patients and blood donor controls." (PMID 31647805, 2019). "CTSG N125S variant G allele (AG +GG) was also more frequent among osteomyelitis patients (8.1% vs. 4.7%, p = 0.01)." (PMID 31647805, 2019). "We describe for the first time an association in adults between the CTSG N125S polymorphism, previously associated with cardiovascular and neurovascular diseases, and osteomyelitis, a bacterial infection of the bone." (PMID 31647805, 2019). "In summary, we describe here a potential association between the CTSG N125S polymorphism and osteomyelitis." (PMID 31647805, 2019). "Serum CTSG activity and LF levels were significantly higher in osteomyelitis patients carrying the G allele compared to those with the AA genotype, (p<0.04)." (PMID 31647805, 2019). "The CTSG gene N125S polymorphism may therefore increase osteomyelitis susceptibility by increasing lactoferrin and CTSG activity." (PMID 39301021, 2024). "However, there are still other plausible explanations of the association of the CTSG polymorphism with osteomyelitis." (PMID 31647805, 2019). "CTSG N125S polymorphism was genotyped in 329 osteomyelitis patients and 415 controls), Blood coagulation parameters, serum CTSG activity, LF, MMP-1, MMP-13, and soluble receptor activator for nuclear factor κ B ligand (sRANKL) levels were assessed in carriers of the different CTSG genotypes." (PMID 31647805, 2019). "However, fibrinogen levels and other blood coagulation parameters were similar in carriers of the different genotypes of the CTSG N125S polymorphism among osteomyelitis patients in our study." (PMID 31647805, 2019). "Differences in the CTSG gene might enhance osteomyelitis susceptibility by increasing CTSG activity and LF levels." (PMID 31647805, 2019). "We also explored the mechanisms whereby the CTSG N125S polymorphism might increase susceptibility to osteomyelitis." (PMID 31647805, 2019). "Perhaps the association of the CTSG N125S polymorphism with osteomyelitis might be mediated by LF." (PMID 31647805, 2019). "In spite of the increased serum CTSG activity associated with the CTSG polymorphism we could speculate that there was abnormal wound healing that could play some role in the enhanced susceptibility to osteomyelitis." (PMID 31647805, 2019). "CTSG N125S (AG) genotype was significantly more frequent among osteomyelitis patients than controls (15.5% vs. 9.4%, p = 0.014)." (PMID 31647805, 2019). "Frequency of CTSG N125S (rs 45567233) genotypes in osteomyelitis (OM) patients and blood donor (controls)." (PMID 31647805, 2019). "The CTSG N125S AG heterozygous genotype was significantly more frequent among osteomyelitis patients compared to controls (15.5% vs. 9.4%; χ2 = 6.5, OR = 1.78, 95% CI = 1.11–2.84, p = 0.011 by the Mantel-Haenszel test, χ2 = 5.95, p = 0.014 by the Yates correction)." (PMID 31647805, 2019). "CTSG N125S polymorphism, a genetic variation that might modify neutrophils CTSG activity could influence osteomyelitis pathogenesis by modifying LF production and subsequent cleavage, MMPs-mediated bone inflammation and remodeling, and activating coagulation." (PMID 31647805, 2019). "The findings suggest potential linkages between SNPs in genes such as IL-1, IL-6, IFN-γ, TNF-α, VDR, tPA, CTSG, COX-2, MMP1, SLC11A1, Bax, NOS2, and NLRP3 with the development of osteomyelitis." (PMID 39301021, 2024).
osteomyelitis (continued). "Current research has amassed increasing evidence suggesting that SNPs in various genes, including IL-1, IL-6, IFN-γ, TNF-α, VDR, tPA, CTSG, COX-2, MMP1, SLC11A1, Bax, NOS2, and NLRP3, may contribute to the development of osteomyelitis." (PMID 39301021, 2024).
psoriasis (4 papers, 2018 to 2025). An autoimmune condition characterized by red, well-delineated plaques with silvery scales that are usually on the extensor surfaces and scalp. "The results indicated that P. clypearia may affect the energy metabolism, cell growth and apoptosis by regulating genes such as Hspa1a, Hspa1b, mt-Nd4l, mt-Nd5, mt-Nd6, Bcl-2, Asns, Trib3, GzmA, CTSG, etc, thereby mitigating psoriasis-related inflammation." (PMID 41385507, 2025). "In summary, here we have identified several novel peptide-based inhibitors of neutrophil-derived cathepsin G or elastase that may have potential as therapeutic modulators of IL-36 cytokine activity in inflammatory conditions such as psoriasis." (PMID 29515113, 2018). "As a result, we found that the mRNA expression level of KIT, ENPP3, CMA1, CTSG, TPSAB1 and TPSG1 is decreased in PP compared with PN and NN, indicating the fraction of total mast cells is decreased in psoriasis." (PMID 34887864, 2021).
vasculitis (4 papers, 2013 to 2022). "Therefore, CTSG is an important factor involved in vasculitis." (PMID 35990842, 2022). "None of the IBD and SpA patients recognized myeloperoxidase antigen, elastase, lactoferrin, proteinase 3, or cathepsin G, indicating that p-ANCA is a different antigen that is specifically recognized in vasculitis." (PMID 29213287, 2017). "Meanwhile, the prevalences of antibodies against the proteinase 3, cathepsin G, lactoferrin, HLE, and azurocidin were significantly higher in patients with PTU-induced vasculitis than those in patients with PTU-induced MPO-ANCA but without clinical vasculitis." (PMID 24252385, 2013).
viral infection (4 papers, 2014 to 2024). "Several genes in this group (CTSG, encoding the neutrophil serin protease Cathepsin G; DEAFA4, defensin alpha 4; LCN2, lipocalin 2; OLFM4, BPI and CD24), are known to be overexpressed in patients with severe viral infections, including COVID-197,14." (PMID 35181735, 2022). "Several differentially expressed genes between the two trajectories (CTSG, PRC1, DEFA4, KIF15, TCEAL9, HMMR, CEP55, and AZU1) were overexpressed in patients with severe viral infection, but not in those with non-severe viral infection compared to HCs." (PMID 33765435, 2021).
atherosclerosis (3 papers, 2013 to 2024). A disease characterized by the build-up of fatty material and calcium deposition in the arterial wall resulting in partial or complete occlusion of the arterial lumen. "While potentially protective, a pro-thrombotic effect from neutrophil cathepsin G might increase risk of pathologic thromboses in individuals with pre-existing pro-thrombotic states as has been described for patients with atherosclerosis and myeloproliferative diseases." (PMID 23940756, 2013).
Autoimmunity (3 papers, 2017 to 2021). The occurrence of an immune reaction against the organism's own cells or tissues. "There is now renewed attention on neutrophils and neutrophil serine proteases (NSPs) such as neutrophil elastase (NE), proteinase 3 (PR3), and cathepsin G (CG) in inflammation and autoimmunity." (PMID 28192517, 2017).
bladder urothelial carcinoma (3 papers, 2020 to 2023). "Immunohistochemistry and online analyses validated the functions of 4 key immune-related genes (LIG1, TBX1, CTSG and CXCL12) in bladder urothelial carcinoma." (PMID 32579540, 2020).
HIV-1 infection (3 papers, 2014 to 2025). The type species of lentivirus and the etiologic agent of acquired immunodeficiency syndrome (AIDS). "Similarly, cathepsin G (CTSG) recruits monocytes/macrophages to inflammatory sites during HIV-1 infection and heightens their viral susceptibility, establishing a positive feedback loop." (PMID 41050696, 2025). "Taken together, these studies suggest a multifactorial role for cathepsin G in enhancing HIV-1 infection." (PMID 27025760, 2014). "Interestingly, prolonged exposure of macrophages to cathepsin G suppressed HIV-1 infection, an effect that was neutralized by the addition of serine protease inhibitors." (PMID 27025760, 2014). "Cathepsin G, a neutrophil-derived serine protease that is present in human CVF, has been reported to bind the HIV-1 envelope protein gp120, and can promote HIV-1 infection of macrophages, but not CD4+ T lymphocytes." (PMID 27025760, 2014).
ischemic stroke (3 papers, 2013 to 2023). A stroke disorder caused by obstruction of blood flow to the brain, due to thrombotic (local blood clot formation) or embolic (due to a blood clot or other material traveling from another site) event. "Previous literature has indicated that neutrophil elastase and/or cathepsin G may be involved in the pathology associated with traumatic brain injury, neuromyelitis optica, and ischemic stroke." (PMID 30149799, 2018). "Particularly, NETs, which consists of DNA coated with histones, myeloperoxidase, elastase, and cathepsin G, has been reported participate in the intracranial hemorrhage and ischemic stroke." (PMID 38144176, 2023). "Inhibition of cathepsin G has also been found to increase cerebral blood flow and reduce infarct volume and neurobehavioral deficits in a mouse model of ischemic stroke." (PMID 30149799, 2018). "In a vaso-occlusive model of ischemic stroke, inhibition of cathepsin G and its congenital absence improved cerebral blood flow, reduced histologic brain injury, and improved neurobehavioral outcome." (PMID 23940756, 2013).
liver cancer (3 papers, 2021 to 2024). An epithelial or non-epithelial malignant neoplasm that arises from the liver. "Previous experimental studies have confirmed that the interplay of tumor cells and neutrophils promotes the metastasis of liver cancer through the cathepsin G component related to NET, indicating a correlation between cathepsin G and HCC." (PMID 38590662, 2024). "Interestingly, we found that most of these key node genes play important roles in tumorigenesis (RET, CEACAM5), immune regulation (CTSG, CD79A) and the EMT pathway (COL10A1, COL11A2), suggesting their significant role in the recurrence of liver cancer." (PMID 34956309, 2021).
lung adenocarcinoma (3 papers, 2023 to 2024). A carcinoma that arises from the lung and is characterized by the presence of malignant glandular epithelial cells. "Another study mentioned that the prognostic model of CTSG gene signatures was significantly associated with overall survival (OS) and tumor microenvironment (TME) immune cells in lung adenocarcinoma." (PMID 39080685, 2024).
lung disease (3 papers, 2018 to 2024). "NSPs include neutrophil elastase, proteinase 3 and cathepsin G. An imbalance between NSPs and their antiproteases has been observed in people with CF lung disease and people with NCFBE." (PMID 39293854, 2024). "In addition, neutrophils, one type of granulocytes, secrete serine proteases including neutrophil elastase, cathepsin G and proteinase-3, as well as MMP-8 and MMP-9, which may lead to destruction of the alveolar tissue and increase the risk of lung disease." (PMID 30400967, 2018).
melanoma (3 papers, 2014 to 2021). A malignant, usually aggressive tumor composed of atypical, neoplastic melanocytes. "Notably, the targets of PEDF, elane (elastase) and cathepsin G, which are indispensible for melanoma metastasis 43 were both significantly induced upon B-16V BAG6KO-EVs treatment in mouse lungs (but not in response to WT-EVs)." (PMID 31534536, 2019).
soft tissue sarcoma (3 papers, 2021 to 2023). A malignant neoplasm arising from muscle tissue, adipose tissue, blood vessels, fibrous tissue, or other supportive tissues excluding the bones. "CTSG was reported as a potential immune-related biomarker in OSCC by a recent study, and it has also been found to be associated with the survival of other cancer types such as soft tissue sarcoma, muscle-invasive bladder cancer, and node-negative breast cancer." (PMID 34497859, 2021). "In soft tissue sarcoma, a signature consisting of SECTM1 and other four immune-related genes, IFIH1, CTSG, STC2, and BIRC5, could predict prognosis and the responses to ICIs23 These evidence further enhanced the correlation of SECTM1 with anti-tumor immunity." (PMID 36818292, 2023). "CTSG is also closely related to the survival of several cancer types, including soft tissue sarcoma, muscular invasive bladder cancer, and lymph node-negative breast cancer, and is a potential immune-related biomarker for OSCC." (PMID 35935989, 2022).
acute lymphoblastic leukemia (2 papers, 2017 to 2022). Leukemia with an acute onset, characterized by the presence of lymphoblasts in the bone marrow and the peripheral blood. "Recent studies have shown that CTSG is an effective target for the immunotherapy of AML and acute lymphoid leukemia (ALL)." (PMID 35111390, 2022).
endometriosis (2 papers, 2022 to 2024). The growth of functional endometrial tissue in anatomic sites outside the uterine body. "Another protein of interest is cathepsin G, of which the expression is downregulated not only in the endometrium in the secretory phase of women with endometriosis but also in their serum." (PMID 35204508, 2022). "This study also revealed that cathepsin G is a common DEP in the urine, serum, and plasma of women with endometriosis." (PMID 39061077, 2024).
endothelial dysfunction (2 papers, 2014 to 2021). In vascular diseases, endothelial dysfunction is a systemic pathological state of the endothelium (the inner lining of blood vessels) and can be broadly defined as an imbalance between vasodilating and vasoconstricting substances produced by (or acting on) the endothelium. "Taken together, this study provides a novel mechanism by which active elastase and cathepsin G originating from primed PMNLs of HD patients can initiate endothelial dysfunction." (PMID 24877096, 2014). "Thus, this study can provide a mechanism by which active elastase and cathepsin G are released from primed PMNLs, mediate VE-cadherin cleavage, and initiate endothelial dysfunction in these patients." (PMID 24877096, 2014).
fungal infections (2 papers, 2019 to 2021). "However, susceptibility to fungal infections was more severe in double NE and CTSG knockout mice." (PMID 31727956, 2019). "The role of NE and cathepsin G is made evident by mice lacking NE or cathepsin G, which are more susceptible to fungal infections." (PMID 34208679, 2021).
Insulin resistance (2 papers, 2022 to 2025). Increased resistance towards insulin, that is, diminished effectiveness of insulin in reducing blood glucose levels. "The current study revealed that several cytokines—including RETN, CTSG, and ELANE, which can promote vascular damage and insulin resistance—were upregulated in the DM R+ group." (PMID 40641746, 2025).
lymph node metastasis (2 papers, 2015 to 2024). "HSP27, slCAM-l, cathepsin G, etc., were up-regulated in NPC patients with lymph node metastasis; NM-23-H1 proteins, etc., were down-regulated in NPC patients with lymph node metastasis." (PMID 26184160, 2015).
metastatic disease (2 papers, 2021 to 2024). "The enzymes elastase, cathepsin G, and MMP9 secreted by neutrophils have been associated with progression in metastatic disease." (PMID 39596977, 2024).
non-small cell lung carcinoma (2 papers, 2024). A group of at least three distinct histological types of lung cancer, including non-small cell squamous cell carcinoma, adenocarcinoma, and large cell carcinoma. "Our study showed that CTSG protein was lowly expressed in non-small cell lung cancer and the expression correlated with the clinical stage." (PMID 39080685, 2024). "The results of the analysis predicted that the expression level of CTSG might have some influence on the survival prognosis of patients with non-small cell lung cancer." (PMID 39080685, 2024). "In non-small cell lung cancer, the expression of CTSG was lower than that in adjacent non-tumor tissues." (PMID 39080685, 2024).